IL10 (interleukin 10)
Diseases named in the same sentence as IL10 in open-access papers (continued):
Sharing a sentence is not in itself a finding about the gene and the disease.
tumor (continued). "Research indicates that vaccine-induced IL-10-producing DCs can impair the priming of anti-tumor responses." (PMID 40076949, 2025). "IL-10 also plays a role in supporting tumor growth by creating an immunosuppressive microenvironment." (PMID 40242222, 2025). "Tumor cells secrete immunosuppressive cytokines, such as interleukin-10 (IL-10), prostaglandin E2, and lymphocyte-activation gene 3 (LAG-3), thereby promoting immune evasion." (PMID 41229433, 2025). "For instance, in cGAMP‐treated pancreatic ductal adenocarcinoma mouse models, Breg cell‐derived IL‐35 and IL‐10 are markedly elevated, and their levels correlate positively with tumour weight." (PMID 41275427, 2025). "Viral and non-viral vector delivery systems have enabled the localized and sustained delivery of therapeutic genes like IL-10 to tumor sites, enhancing its anti-inflammatory and tumor-modulating effects." (PMID 40149345, 2025). "STAT3, activated downstream of IL-6 or tumor-derived cytokines, orchestrates expression of arginase-1, IL-10, and CD163—key mediators of immunosuppressive reprogramming." (PMID 41459539, 2025). "Tumor cells establish a hypoxic and acidic environment, accompanied by the release of large quantities of immunosuppressive cytokines such as IL-10 and TGF-β." (PMID 40292299, 2025). "It inhibits pro-inflammatory responses, and IL-10 helps maintain an environment that favors tumor survival, leading to poor prognosis as it allows EwS tumors to grow unchecked." (PMID 40242222, 2025). "Intratumoral migrasome-rich fibroblasts activated B regulatory pathways via dual IL-10/TGFβ signaling, whereas juxta-5μm low-migrasome counterparts facilitated stromal-tumor cooperativity through MMP9/VEGF-A axis activation." (PMID 40443671, 2025). "For example, chronic Candida infection can secrete immunosuppressive factors such as IL-10, thereby inhibiting the activity of effector immune cells and supporting tumor cell growth and immune evasion." (PMID 40557321, 2025). "In tumor proliferation and metastasis, IL-13, IL-4, and IL-10 in TME induce macrophages to polarize to the M2 phenotype." (PMID 40297580, 2025). "Second, these macrophages release a spectrum of immunoregulatory factors such as TGF-β, IL-10, Arg-1, and nitric oxide (NO) which sustain an immunosuppressive microenvironment conducive to tumor expansion." (PMID 41058699, 2025). "For example, IL-10 has shown potential to promote anti-tumor immunity in a variety of mouse models, including by enhancing mitochondrial oxidative phosphorylation of macrophages, thereby enhancing the effectiveness of immunotherapy." (PMID 41226585, 2025). "Blocking both IL-17A and IL-10 can increase the tumor response to PD-1/PD-L1 inhibitor immunotherapy in patients with MSS mCRC." (PMID 41051603, 2025). "In tumor tissue (TT), their numbers are typically reduced, and their functions are inhibited by tumor cytokines, such as interleukin-10 (IL-10), resulting in the emergence of immune tolerance and the proliferation of regulatory T cells (Tregs)." (PMID 41228278, 2025). "These molecular interactions highlight the multifaceted and selective nature of IL-10 signaling pathways, further emphasizing its relevance in the context of tumor resistance." (PMID 40507238, 2025). "Random forest analysis identified tumor stiffness, IL-10, and TNF-α as the strongest predictors of therapeutic outcome." (PMID 41391724, 2025). "This process fosters a dynamic microenvironment marked by tissue repair and the presence of mediators such as IL-1, IL-10, and IL-7, which bolster the immune response and enhance therapeutic efficacy while mitigating tumor regrowth." (PMID 40420174, 2025). "It was demonstrated that in sGRP78hi TNBC patients, more Tregs and regulatory IL‐10+ B cells infiltrated into tumor tissues." (PMID 40936109, 2025).
tumor (continued). "Excessive immune activation further recruits M2 macrophages, which enhance PD-L1-mediated immunosuppression via IL-10 and TGFβ1, thus reducing cytotoxic T-cell tumor infiltration and promoting tumor recurrence." (PMID 41006707, 2025). "TAMs, which constitute up to 50% of the tumor mass, adopt an anti-inflammatory phenotype, secreting cytokines such as interleukin-10 (IL-10) and transforming growth factor-beta (TGF-β) that inhibit effector T cell activity." (PMID 40223940, 2025). "Evaluating the equilibrium between IFN-γ and anti-inflammatory cytokines (IL-4 + IL-10 + IL-13) revealed tumor progression is accompanied by an increased inflammatory balance in 4T1 tumors (P=0.0004), in contrast to MC4-L2 tumors." (PMID 39877637, 2025). "IL-10 also promotes activation of tumor-resident CD8+ T cells, retards tumor growth, and induces IFN-γ–dependent tumor cell death and metastasis suppression in murine BC models." (PMID 40868199, 2025). "M2 macrophages have the ability to secrete a diverse array of complex cytokines including IL-1β, IL-6, IL-10 as well as Arg-1, which regulates Th2-type immune responses and promotes tumor growth and metastasis." (PMID 40599798, 2025). "In macrophages, NPs modulate cytokines such as Tumor Necrosis Factor (TNF)-α, nitric oxide (NO), interleukin-(IL)−10 (IL-10), and IL-1beta (IL-1β) secretion in both tumor and non-tumor cells." (PMID 40643749, 2025). "In contrast to CD8+, CD4+ T-cell infiltration shows mixed prognostic associations, as subsets like Tregs (CD4+FoxP3+) actively suppress CD8+ effector function through TGF-β, IL-10, and adenosine-mediated pathways, blunting anti-tumor immunity." (PMID 41007774, 2025). "The further study found that the STAT1/STAT3 signaling pathway in tumor cells activated by IL-10 inhibited the PERK signaling pathway and alleviated the ER stress-mediated cell death in tumor cells caused by CAP treatment." (PMID 41145470, 2025). "Bregs hinder the synthesis of IL-17 and IFN-γ by Th17 and Th1 cells, respectively, and prevent the differentiation of Th17 cells within the tumor microenvironment in an IL-10-dependent manner." (PMID 40292299, 2025). "F. nucleatum, while more studied in colorectal cancer, is recognized as an immunomodulatory microbe that can promote IL-10 production, suppress cytotoxic immune activity, and create a tumor-promoting microenvironment." (PMID 41030253, 2025). "Th-cells include Th1, which produce IL-2, IFN-γ, and TNF-β to activate CTLs and other immune cells, and Th2, which release IL-4, IL-5, IL-6, and IL-10, encouraging tumor growth through CD40-CD40L interactions." (PMID 40299416, 2025). "Bregs contribute to tumor immune evasion by secreting IL‐10, IL‐35, and TGF‐β, which inhibit T‐cell activity and promote immune tolerance." (PMID 40356222, 2025). "IL-10 can promote the formation of an immunosuppressive microenvironment and facilitate T cell immune suppression and tumor escape." (PMID 41050654, 2025). "In contrast, IL-10 is an immunoregulatory cytokine mainly produced by regulatory and helper T lymphocytes, as well as by tumor cells within the tumor microenvironment." (PMID 41019059, 2025). "These cancer cells release NAA into the tumor microenvironment, where it acts in synergy with IL-10 to polarize TAMs toward an M2-like, protumoral state." (PMID 40330466, 2025). "At the same time, some cellular components of TME secrete immune-suppressive factors such as TGF-β and IL-10, which inhibit the antitumor activity of immune cells in peripheral blood, helping tumor cells evade surveillance by the host immune system." (PMID 40427733, 2025). "Future research can further explore the artificial engineering of IL-4, IL-10, and other cytokines to remodel their immune regulatory functions, thus expanding their application prospects in tumor immunotherapy." (PMID 41226585, 2025). "IL-10 acts as a key intercellular regulator of immune and inflammatory responses, exerting context-dependent effects on tumor immunity." (PMID 41515435, 2025).
tumor (continued). "Suppressing IL-12 and other M1-associated cytokines while promoting IL-10, TGF-β, and miR-146a allows macrophages to support tumor immune evasion." (PMID 40647470, 2025). "Vorinostat effectively inhibits HDAC6 expression, induces cancer cell apoptosis, and reduces EAOC tumor size by blocking the ARID1A6488delG/HDAC6/IL-10 pathway." (PMID 40330466, 2025). "In this cancer, large amounts of IL-10 released by cells surrounding the tumor inhibit IL-12 production by cDC1 and suppress the T cell response, promoting cancer development and metastasis." (PMID 40136652, 2025). "Essentially, IL-10 acts to dampen anti-tumor immune responses: it inhibits the activation of Th1 responses, reduces cytotoxic T cell and NK cell activity, and upregulates expression of checkpoint molecules on antigen-presenting cells." (PMID 41007766, 2025). "These cells release a spectrum of immunosuppressive cytokines, including transforming growth factor-beta (TGF-β) and interleukin-10 (IL-10), which further diminish the activity of effector T cells and promote tumor tolerance." (PMID 39833954, 2025). "These cells then generate an immunosuppressive TME via the secretion of anti-inflammatory cytokines such as IL-10 and TGFβ which impede NK cell and T cell anti-tumour immunity." (PMID 40291981, 2025). "IL-10 inhibits the functions of dendritic cells and macrophages needed to present tumor antigens effectively, leading to fewer tumor-specific T cells." (PMID 41007766, 2025). "SNORA38B drives tumor progression by stimulating secretion of interleukin-10, which recruits regulatory T cells and reduces infiltration of CD3+ and CD8+ T cells in non-small cell lung cancer (NSCLC)." (PMID 39815331, 2025). "In the tumor microenvironment, immunosuppressive factors (such as IL-10 and TGF-β) often suppress immune cell function, allowing tumor cells to escape immune system attack." (PMID 40370453, 2025). "Butyrate derivatives from probiotics negatively regulate the NLRP3-mediated inflammatory signaling pathway, inhibit the activation of associated macrophages, and reduce their expression levels of PD-L1 and IL-10, thereby suppressing tumor growth in mice." (PMID 40529304, 2025). "Although macrophages naturally migrate to sites of inflammation, tumour-associated immunosuppressive signals such as IL-10, TGF-β, and hypoxiacan impair their recruitment or reprogram them toward an M2-like, tumour-supporting phenotype." (PMID 40574837, 2025). "For example, CRT and other DAMPs can be used to enhance the efficacy of DC vaccines, or IL-10 signaling can be blocked to reverse the immunosuppressive microenvironment, thereby optimizing the anti-tumor immune response." (PMID 40535125, 2025). "Cytokines, including TNF-α, IL-10, IL-8, and IL-6, are also released by the tumor stroma, and are identified as chemotactic, immunosuppressive, and pro-survival signals, further supporting EMT induction." (PMID 39941895, 2025). "Evidence has shown that activation of STAT3 stimulated by IL-10 and TGFβ in tumor-infiltrating DCs impedes CD8+ T cell function, and contributes to accumulation and proliferation of tolerogenic Treg cells inside tumors." (PMID 38245798, 2024). "Elevated concentrations of proinflammatory mediators, including interleukin 6 (IL-6), IL-8, IL-10 in CF tumor tissue prompted the use of tocilizumab and bevacizumab, achieving a decrease in cystic disease after initiation of combination therapy." (PMID 39634188, 2024). "These macrophages elevate the levels of proangiogenic factors such as VEGF, TGF-β, and IL-10 in the tumor microenvironment to induce an angiogenic response towards the engrafted CoM cells in vivo." (PMID 38842752, 2024). "Tumor cells predominantly express Th2 type cytokines, such as IL-4, IL-6, and IL-10 which aid tumor cells in evading immune destruction by inhibiting the differentiation of CD8+ T cells." (PMID 38255791, 2024).
tumor (continued). "A correlation between high tumor burden and low anti-inflammatory response (IL-10 secretion) was unexpected at first glance." (PMID 38473247, 2024). "This treatment significantly reduces Treg frequency, diminishes the production of TGF-β and IL-10 by Tregs, and also safeguards tumor-antigen-specific CD8+ T cells from tumor-induced deletion in the context of HCC." (PMID 38791916, 2024). "Conversely, 2‐ME‐treatment resulted in fewer CD163+ cells detectable in the TME, increased levels of tumor necrosis, increased IL‐10 plasma levels, and low IL‐6 and IL‐27 plasma levels." (PMID 38600057, 2024). "The immune-suppressive environment, supported by myeloid-derived suppressor cells (MDSCs) and cytokines such as IL-10, further limits the efficacy of immune checkpoint inhibitors, sustaining tumor survival." (PMID 39682256, 2024). "Depletion of Nrp2 in TAMs (Nrp2fl/flCSF1R-iCre) inhibited efferocytosis and transcription of anti-inflammatory factors IL-10, IL-4, TGFβ, PD-L2 while promoting IL-12 and IFNβ expression, collectively slowing tumor growth in mouse pancreatic cancer." (PMID 38592275, 2024). "In contrast, M2 macrophages are considered to promote tumor initiation and progression via immunosuppressive cytokines like IL-10 and TGF-β." (PMID 38203835, 2024). "For instance, Tregs can convert to Th1 or Th17 types, while Th1 cells secrete cytokines like IFN-γ and IL-2 that enhance anti-tumor immunity, and Th2 cells release IL-4 and IL-10, which can promote tumor growth." (PMID 39769334, 2024). "These M2-type macrophages inhibit anti-tumor immune responses and promote tumor growth and metastasis by secreting a variety of immunosuppressive factors (e.g., IL-10, TGF-β) and factors that promote tumor angiogenesis (e.g., VEGF)." (PMID 39416792, 2024). "The elevated expression of 1L10 in malignant T cells facilitates tumor growth in vivo through IL10-mediated macrophage infiltration and M2 polarization." (PMID 39409988, 2024). "Some studies on the other hand suggested that IL-10 can be used as an immunotherapy in tumor models." (PMID 38520006, 2024). "IL-10 neutralization in ascites reverses the immunosuppressive effects of MDSCs, improving survival and alleviating tumor burden in OC patients." (PMID 38279997, 2024). "Macrophages derived from tumor-infiltrating monocytes secrete IL-10 and TGF-β to promote immunosuppression and mediate T lymphocyte dysfunction, allowing immune escape and tumor growth." (PMID 38370351, 2024). "Particularly, the ability to induce mucus layer degradation or modulate IL-10 by the B. fragilis polysaccharide A (PSA) can be responsible for an immunosuppressed microenvironment that favours tumour progression." (PMID 38970018, 2024). "M2 macrophages secrete immunosuppressive cytokines and chemokines like TGF-beta and IL-10, promoting tumor progression." (PMID 39119332, 2024). "CpG oligodeoxynucleotides (CpG ODNs) emulate bacterial DNA and induce anti-tumor effects by activating the immune system when the immunosuppressive function of IL-10 is inhibited via targeting IL-10, IL-10R, or STAT3." (PMID 39767682, 2024). "In the tumor microenvironment, various factors beyond M-CSF and GM-CSF have been shown to regulate macrophage maturation, including IL-3, IL-10, TGF-β, and physical factors such as extracellular matrix and hypoxia." (PMID 38424542, 2024). "In the present study, the fusion with human IgG1 Fc in Nb‐TriTE enhanced the secretion of GM‐CSF, MCP‐1, eotaxin, and pro‐inflammatory cytokines, while reducing immunosuppressive cytokine IL‐10 secreting from PBMCs when challenged with tumor cells." (PMID 39234811, 2024). "Patients with tumor, or high IL-6 or elevated IL-10 expression exhibited a significantly shorter survival time." (PMID 38173531, 2024). "M2 macrophages promote tumor progression through immune suppression, secretion of anti-inflammatory cytokines like IL-10 and TGF-β, and factors supporting angiogenesis and extracellular matrix remodeling." (PMID 39872527, 2024).
tumor (continued). "IL-10 is known for its ability to suppress effective antitumor immune responses, thereby enhancing tumor immune evasion and progression." (PMID 39456897, 2024). "IL-10 influences the ability of tumor cells to proliferate, invade, and metastasize by inhibiting apoptotic signaling pathways and modulating cytokine production and release." (PMID 39840050, 2024). "Tregs release related factors such as TGF-β and IL-10/35, downregulating anti-tumor immunity and inhibiting antigen presentation by dendritic cells (DCs), further dampening immune responses by lymphocytes." (PMID 39421736, 2024). "IL-10/IL-10R neutralization has demonstrated more anti-tumor effects when combined with other immunotherapeutic strategies." (PMID 38279997, 2024). "On the other hand, evidence indicates that IL-10 also possesses immunostimulatory and anti-tumor properties, including the inhibition of angiogenesis and matrix metalloproteinase 2, thereby inhibiting metastasis." (PMID 39195299, 2024). "Specifically, GBMs can recruit immunosuppressive cells, such as myeloid cells, to the tumor microenvironment (TME) that can release anti-inflammatory cytokines such as IL-10, leading to T cell exhaustion and immunosuppression." (PMID 39409893, 2024). "Tumor-derived factors (i.e., IL-6, IL-10, IL-1β, PGE2, VEGF, GM-CSF, M-CSF, and IFN-γ) have been reported to induce MDSCs." (PMID 39272914, 2024). "The relationship between IDO1 and marker genes of tumor-associated macrophages (TAMs; CCL5, CD68, and IL10), M1 (IRF5, NOS2, and PTGS2), and M2 (CD163, VSIG4, and MS4A4A) macrophages was analyzed." (PMID 39351094, 2024). "The anti-inflammatory, immune-suppressive cytokine IL-10, secreted by both tumor cells and immune cells, promotes cancer progression by inhibiting the anti-tumor response via different signaling pathways." (PMID 39335188, 2024). "Conversely, M2 macrophages, activated by IL-4 and IL-10, contribute to tumor progression and metastasis." (PMID 38293522, 2024). "MDSCs promote tumor progression and enhance tumor cell survival, angiogenesis, invasion, metastasis, and the production of immunosuppressive cytokines such as IL-10 and TGF-b)." (PMID 38762523, 2024). "Silencing of IL-10 expression through inoculation of tumours with shRNA-IL-10 lentivectors inhibited MDSCs and suppressed cancer growth via enhanced anti-tumour type 1 immune response." (PMID 38464388, 2024). "This idea was corroborated by the finding that IL-10 promotes both survival and proliferation of tumor cells by stimulating STAT3 activation, at the same time hampering tumor antigen presentation to immune cells, which enhances evasion of immune surveillance." (PMID 39281678, 2024). "Oncogenic activation of the MAPK pathway is known to lead to the secretion of cytokines such as VEGF and IL-10, known to dampen T-cell activity and recruitment to tumor sites." (PMID 38629578, 2024). "Studies have shown that overexpression of IL-10 in human cancer models promotes tumor rejection, induces durable immunity, and enhances the cytotoxicity of CD8+ T cells." (PMID 39411143, 2024). "Following differentiation, Th2 cells secrete IL-4, IL-5, IL-10, IL-13, and IL-17 and eventually undergo tumor growth and metastasis." (PMID 38238581, 2024). "This interaction drives TAMs to secrete anti-inflammatory cytokines, such as TGF-β and IL-10, as well as pro-tumor factors like VEGF and EGF, thereby supporting tumor growth, promoting angiogenesis, and suppressing immune responses." (PMID 39575419, 2024). "CXCL12 recruits regulatory B cells into the tumor which can exacerbate tumor progression via IL-10 and TGF-β expression." (PMID 38726320, 2024). "Tumor-associated neutrophils (TANs) can inhibit T cell responses through expression of ARG1, PDL1, IL-10, and ROS, and TANs can actually induce CD8 T cell apoptosis through NO production and the TNFα pathway." (PMID 38254801, 2024).